PSMC1 (proteasome 26S subunit, ATPase 1)
Description:
Component of the 26S proteasome, a multiprotein complex involved in the ATP-dependent degradation of ubiquitinated proteins. This complex plays a key role in the maintenance of protein homeostasis by removing misfolded or damaged proteins, which could impair cellular functions, and by removing proteins whose functions are no longer required. Therefore, the proteasome participates in numerous cellular processes, including cell cycle progression, apoptosis, or DNA damage repair. PSMC1 belongs to the heterohexameric ring of AAA (ATPases associated with diverse cellular activities) proteins that unfolds ubiquitinated target proteins that are concurrently translocated into a proteolytic chamber and degraded into peptides.
Synonyms: P26s4; S4; p56; RPT2; NEDGTH
Tractability: Small molecule: an approved drug acts on it; a structure with a bound ligand is known; a high-quality ligand is known. PROTAC: UniProt records ubiquitination sites on it; ubiquitination databases record sites on it; its protein half-life has been measured.
Target class: Enzyme
Gene: Protein-coding gene on chromosome 14 (90,256,527 to 90,275,429, forward strand). Ensembl gene ENSG00000100764.
Subcellular location: Cytoplasm; Nucleus; Membrane
Subcellular location (Human Protein Atlas): Cytosol; Nucleoplasm
Pathways (Reactome):
Immune System: AMPK-induced ERAD and lysosome mediated degradation of PD-L1(CD274); Activation of NF-kappaB in B cells; Antigen processing: Ubiquitination & Proteasome degradation; CLEC7A (Dectin-1) signaling; Cross-presentation of soluble exogenous antigens (endosomes); Dectin-1 mediated noncanonical NF-kB signaling; Downstream TCR signaling; ER-Phagosome pathway; FCERI mediated NF-kB activation; GSK3B-mediated proteasomal degradation of PD-L1(CD274); Interleukin-1 signaling; NIK-->noncanonical NF-kB signaling; SPOP-mediated proteasomal degradation of PD-L1(CD274); TNFR2 non-canonical NF-kB pathway
Cell Cycle: APC/C:Cdc20 mediated degradation of Securin; APC/C:Cdh1 mediated degradation of Cdc20 and other APC/C:Cdh1 targeted proteins in late mitosis/early G1; Autodegradation of Cdh1 by Cdh1:APC/C; Autodegradation of the E3 ubiquitin ligase COP1; Cdc20:Phospho-APC/C mediated degradation of Cyclin A; FBXL7 down-regulates AURKA during mitotic entry and in early mitosis; G2/M Checkpoints; SCF(Skp2)-mediated degradation of p27/p21; SCF-beta-TrCP mediated degradation of Emi1; Separation of Sister Chromatids; The role of GTSE1 in G2/M progression after G2 checkpoint; Ubiquitin-Mediated Degradation of Phosphorylated Cdc25A; Ubiquitin-dependent degradation of Cyclin D
Signal Transduction: Asymmetric localization of PCP proteins; Degradation of AXIN; Degradation of DVL; Degradation of GLI1 by the proteasome; Degradation of GLI2 by the proteasome; Degradation of beta-catenin by the destruction complex; GLI3 is processed to GLI3R by the proteasome; Hedgehog 'on' state; Hedgehog ligand biogenesis; MAPK6/MAPK4 signaling; Negative regulation of NOTCH4 signaling; Regulation of PTEN stability and activity; Regulation of RAS by GAPs
and 28 more pathways
Gene Ontology:
Molecular function: protein binding; RNA binding; proteasome-activating activity; ATP binding; ATP hydrolysis activity
Biological process: cellular response to type I interferon; proteasomal protein catabolic process; proteasome-mediated ubiquitin-dependent protein catabolic process; regulation of proteasomal protein catabolic process; response to oxidative stress
Cellular component: cytosol; membrane; nucleoplasm; nucleus; proteasome complex; proteasome accessory complex; synaptic vesicle; cytoplasm; proteasome regulatory particle
Genetic constraint (gnomAD): Loss-of-function variants: 5 observed, 40.79 expected, observed/expected ratio (o/e) 0.12, 90% interval 0.063 to 0.26. The upper end of that interval is the gene's LOEUF score, 0.26, which puts it in group 1 of 6, group 1 being the genes least tolerant of losing a copy. Missense variants: 159 observed, 465.11 expected, observed/expected ratio (o/e) 0.34, 90% interval 0.3 to 0.39. Synonymous variants: 140 observed, 165.76 expected, observed/expected ratio (o/e) 0.84, 90% interval 0.74 to 0.97.
Homologues: Orthologues: guinea pig PSMC1 (100% identical), macaque PSMC1 (100% identical), mouse Psmc1 (100% identical), pig PSMC1 (100% identical), rabbit PSMC1 (100% identical), rat Psmc1 (100% identical), tropical clawed frog psmc1 (100% identical), zebrafish psmc1a (98% identical), zebrafish psmc1b (97% identical), Drosophila melanogaster Rpt2 (91% identical), Caenorhabditis elegans rpt-2 (84% identical), dog PSMC1 (83% identical). Paralogues in human: PSMC4 (44% identical), PSMC5 (42% identical), PSMC3 (41% identical), PSMC2 (39% identical), PSMC6 (36% identical).
Diseases named in the same sentence as PSMC1 in open-access papers:
PSMC1 is named in the same sentence as 33 diseases in open-access papers, as found by Europe PMC text mining. Sharing a sentence is not in itself a finding about the gene and the disease. The quoted sentences say what the papers report.
breast carcinoma (4 papers, 2020 to 2025). "MIDN interacted with NR4A1, EGR1, and PSMC1, and it was especially co-expressed in liver cancer, pancreatic cancer, urothelial cancer, breast cancer and melanoma." (PMID 40002690, 2025). "Both mRNA and protein levels of PSMC2, PSMC3, PSMC4, PSMC5, and PSMC6 were significant in cancer tissues, and PSMC1, PSMC3, PSMC4, PSMC5, and PSMC6 overexpression was associated with poor prognoses of breast cancer patients." (PMID 34329194, 2021). "Based on the Human Protein Atlas (HPA) database, we found that MIDN, NR4A1, PSMC1, and EGR1 were all positively expressed in liver cancer, pancreatic cancer, urothelial cancer, breast cancer, and melanoma." (PMID 40002690, 2025). "Meanwhile, we discovered that high levels of PSMC1, PSMC3, PSMC4, PSMC5, and PSMC6 transcripts were positively correlated with poor survival, which likely shows their importance in breast cancer development." (PMID 34329194, 2021). "The data demonstrated that PSMC1-6 presented moderate protein expressions, and PSMC2, PSMC3, and PSMC5 were highly expressed in certain clinical tissues from breast cancer specimens." (PMID 34329194, 2021). "NR4A1, PSMC1, and EGR1 were selected as MIDN-interacted proteins, and these four molecules were co-expressed in pancreatic cancer, liver cancer, urothelial cancer, melanoma, and breast cancer." (PMID 40002690, 2025). "We obtained coexpression profiles for PSMC1 from TCGA and METABRIC breast cancer datasets." (PMID 34329194, 2021). "The Kaplan–Meier plotter database also showed that PSMC1, PSMC3, PSMC4, PSMC5, and PSMC6 had high expression levels in breast cancer tissues may have oncogenic roles in breast cancer progression." (PMID 34329194, 2021).
lung adenocarcinoma (4 papers, 2020 to 2022). A carcinoma that arises from the lung and is characterized by the presence of malignant glandular epithelial cells. "This study explored the prognostic and therapeutic potentials of multiple Proteasome 26S Subunit, ATPase (PSMC) family of genes (PSMC1-5) in lung adenocarcinoma (LUAD) diagnosis and treatment." (PMID 35938038, 2022). "Seven other 26S/20S proteasome subunits were isolated (q < 0.05; PSMD12, PSMB4, PSMA6, PSMB6, PSMC1, PSMD3, and PSMB3), illuminating the importance of the 26/20S proteasome integrity in lung adenocarcinoma genome maintenance." (PMID 34070461, 2021).
colorectal cancer (2 papers, 2022 to 2024). A primary or metastatic malignant neoplasm that affects the colon or rectum. "The co-expression analysis revealed that SLIRP is the top and highly co-expressed gene of PSMC1 which was shown to have prognostic roles in colorectal cancer." (PMID 35938038, 2022).
lung carcinoma (2 papers, 2018 to 2022). "For further validation, we explored the role of PSMC1 in the progression of lung cancer through in vitro experiments." (PMID 36091041, 2022). "However, the exact mechanisms by which PSMC1, P2RX1, and GJB3 are involved in the progression of lung cancer have not yet been reported in the literature and warrant further exploration." (PMID 36091041, 2022).
arbovirus infection (1 paper, 2024). A viral infection that is transmitted by an arthropod. "Given that PSMC1 is a proteasome subunit, we asked if treatment of LD652 cells with the proteasome inhibitor bortezomib (Bort) would alter their susceptibility to arbovirus infection." (PMID 38753575, 2024).
prostate carcinoma (1 paper, 2012). A carcinoma that arises from epithelial cells of the prostate gland. "We identified and validated four candidate genes (AKT1, PSMC1, STRADA, and TTK) that impaired growth when silenced in androgen receptor positive prostate cancer cells and enhanced the antiproliferative effects of antiandrogens." (PMID 22509301, 2012). "Although PSMC1 did not score in the PC3 cells in the initial shRNA library screen, siRNA knockdown of PSMC1 impaired viability of PC3 cells, raising the possibility that these antiproliferative effects may not be specific to AR-positive prostate cancer cells." (PMID 22509301, 2012).
sarcoma (1 paper, 2023). A usually aggressive malignant neoplasm of the soft tissue or bone. "Particularly, the expression levels of other proteasome pathway genes, including PSMC1, PSMB6, PSMC2, and PSMB10 seemed to be differentially expressed in MFS/US sarcomas." (PMID 37185612, 2023).
triple-negative breast carcinoma (1 paper, 2021). An invasive breast carcinoma which is negative for expression of estrogen receptor (ER), progesterone receptor (PR), and human epidermal growth factor receptor 2 (HER2). "For example, overexpression of PFN1 is associated with PSMC1 in the MDA-MB-231 triple-negative breast cancer cell line and may involve multiple mechanisms for cancer progression." (PMID 34329194, 2021).
cancer (10 papers, 2015 to 2024). A tumor composed of atypical neoplastic, often pleomorphic cells that invade other tissues. "Our research observed that methylation of PSMC1 was related to BC risk, which can provide more information about PSMC1 gene and cancers from the perspective of epigenetic changes." (PMID 35223499, 2022). "Moreover, elevated SHOC2 and PSMC1 expression has been associated with poorer clinical outcomes among cancer patients." (PMID 38753575, 2024). "As in par with the PSMC1 expression level in comparison with cancer stages, its expression level was also found at the highest threshold in N0 and N3 of the nodal metastasis status group in LUAD patients." (PMID 35938038, 2022). "On the contrary, in terms of cancer stages, PSMC1 showed the highest expression level in stage 1 and stage 4 whereas the intermediate stages showed a downward trend in expression in LUAD tissues although the expression level still remained above that in normal lung tissues (p < 0.001)." (PMID 35938038, 2022). "For instance, seven PSM genes (i.e. PSMA1, PSMA4, PSMC1, PSMC3IP, PSMD13, PSMG2-3 (PSM class I/II/V)) were overexpressed in the majority of the 16 cancer types." (PMID 36123629, 2022). "Interestingly, we discovered that PSMC genes were overexpressed in a subtype-specific manner: specifically, PSMC1, PSMC2, PSMC3, PSMC4 were highly expressed in the triple-negative subtype, PSMC5 in HER-2, and PSMC6 in luminal cancer." (PMID 34329194, 2021).
infection (5 papers, 2020 to 2024). The state of being infected such as from the introduction of a foreign agent such as serum, vaccine, antigenic substance or organism. "We showed that 786–0 cells became sensitive to VSV-M51R infection after either overexpression of IpaH4 or knockdown of IpaH4 substrates, PSMC1 and SHOC2." (PMID 38753575, 2024). "The infection percentage of ASFV in MA-104 cells transfected with PSMC1 plasmid were 8.4% and 13.2%, at 24 and 36 hpi, respectively." (PMID 34578385, 2021). "After 24 h of infection, the expression levels of UBE2C and PSMD6 the expression levels returned to unstimulated baseline levels, while SUMO1, SUMO2 and PSMC1 showed slightly higher expression levels than uninfected control cells." (PMID 37165081, 2023). "Interestingly, at least 2/3 and 3/3 siRNAs targeting SHOC2 and PSMC1, respectively, sensitized 786–0 cells to VSV-M51R-GFP infection." (PMID 38753575, 2024).
tumor (2 papers, 2024). "Importantly, both SHOC2 and PSMC1 are often up-regulated in human malignancies and have been linked to cellular transformation and tumor metastasis." (PMID 38753575, 2024). "This reduction in EGFR expression could elucidate the mechanism behind the observed decrease in tumor aggressiveness and increased afatinib sensitivity, highlighting the therapeutic potential of inhibiting PSMC1 and PSMD11 in LUAD." (PMID 38557672, 2024).
PSMC1 also shares sentences with these, for which no sentence is quoted: melanoma (3 papers); liver cancer (2); ovarian carcinoma (2); pancreatic cancer (2); bladder cancer (1); brain disease (1); cervical cancer (1); chronic myelogenous leukemia (1); co-infection (1); COVID-19 (1); endometrial carcinoma (1); Epstein-Barr virus infection (1); glottic carcinomas (1); head and neck cancer (1); Hypertension (1); kidney renal cancer (1); leukemia (1); myelodysplastic syndrome (1); Parkinson’s- (1); retinal degeneration (1); retinitis pigmentosa (1); schizophrenia (1).